BRCA2 (BRCA2 DNA repair associated)
Diseases named in the same sentence as BRCA2 in open-access papers (continued):
Sharing a sentence is not in itself a finding about the gene and the disease.
cancer (continued). "PARP1 inhibitors are used in cancer therapies in the setting of BRCA1 (breast cancer type 1 susceptibility protein) or BRCA2 (breast cancer type 2 susceptibility protein) loss (olaparib and rucaparib approved by FDA in patients with HR dysfunction)." (PMID 29306194, 2018). "The most commonly mutated cancer susceptibility genes were BRCA2 (n = 31), BRCA1 (n = 22), ATM (n = 19), and MUTYH (n = 19)." (PMID 29684080, 2018). "The majority of cancers were seen in BRCA2 mutation carriers, which is consistent with previously reported data." (PMID 29433453, 2018). "In this study, we have attempted to compile pathogenic and likely pathogenic BRCA1 and BRCA2 variants identified in the main Genetic Cancer Risk Assessment centers in Brazil." (PMID 29907814, 2018). "Reciprocally, this RNAPII antibody also co-immunoprecipitates full-length BRCA2 and the cancer-associated BRCA29000insA truncated mutant protein (lanes 1–6)." (PMID 29386125, 2018). "Inherited mutations inactivating the BRCA2 tumor suppressor gene predispose to cancers of the breast, ovary, pancreas, prostate, and other tissues." (PMID 29386125, 2018). "Pathogenic variants in the highly penetrant susceptibility genes BRCA1 and BRCA2 confer an increased lifetime risk of breast, ovarian and other cancers." (PMID 30400234, 2018). "Although the spliceogenic nature of the BRCA2 c.68‐7T > A variant has been demonstrated, its association with cancer risk remains controversial." (PMID 29460995, 2018). "Our findings provide a robust classification of the BRCA2 c.68‐7T > A variant with respect to its effect on cancer risk, and add evidence that splicing pattern alterations do not necessarily lead to pathogenicity." (PMID 29460995, 2018). "Recently, the cluster regions within BRCA1 and BRCA2 associated with specific cancers have been well established." (PMID 30089478, 2018). "The finding that Brca2 has significant effects on gene expression in both cultured cells and in vivo has implications for the role of BRCA2 mutations in cancer susceptibility." (PMID 29447171, 2018). "We therefore looked for additional rare, and moderate or high impact variants in either HBOC panel genes or candidate genes (involved in DNA repair/ cell cycle and with cancer associations in HGMD) amongst the four BRCA2 K3326* carriers." (PMID 28591191, 2017). "Further well-designed studies are warranted to clarify the mechanism and increase comprehensive understanding of the role of the BRCA2 rs144848 polymorphism in cancer." (PMID 28418854, 2017). "The identification of a carrier of a pathogenic variant in BRCA1 or BRCA2 can significantly impact their medical management, as well as that of at-risk family members, since several cancer risk-reducing strategies are available." (PMID 29161300, 2017). "BRCA2 is a well-known cancer susceptibility gene involved in the repair of double-stranded DNA breaks which functions by regulating the intracellular shuttling and activity of RAD51, another critical protein in homologous recombination." (PMID 28418854, 2017). "One variant, rs11571833, in the BRCA2 gene, was described previously as being associated with an increased risk of developing a variety of cancer types including lung, breast, prostate, gastric and aerodigestive tract cancer." (PMID 28502252, 2017). "Under this circumstance, if BRCA2 is also mutated, the dual effects make repair abnormal and lead to cancer cell death." (PMID 28410213, 2017). "The most popular example exploits the dependency of BRCA1 and BRCA2 deficient cancers on the base excision repair protein PARP1, leading to the development of PARP inhibitors (PARPi)." (PMID 28239445, 2017). "Defective homologous recombination (HR)-mediated DNA repair as a result of mutations in BRCA1/BRCA2 genes is related to genomic instability and generates a unique sensitivity in cancer cells to DNA-targeting agents, which induce irreversible DNA damages." (PMID 29156578, 2017).
cancer (continued). "Unfortunately, germline mutations in BRCA1 and BRCA2 can explain high cancer risk only in a fraction (~20%) of the BC families." (PMID 28649653, 2017). "In an early study of women with a BRCA1 or BRCA2 mutation, 33 biopsies revealed seven cancers (21.2%)." (PMID 28265306, 2017). "Genetic testing for BRCA1 and BRCA2 has led to the accurate identification of individuals at higher risk of cancer and the development of new therapies." (PMID 28222693, 2017). "In a system with a defective HR DNA repair, as it is the case for BRCA2 mutation carriers, this SNP would contribute to higher genome instability and finally to a higher cancer risk for this specific group of patients." (PMID 29383107, 2017). "Women with BRCA1 or BRCA2 gene mutations should undergo annualbreast cancer screening with magnetic resonance imaging from theage of 25 onward, as should women who have first-degreerelatives with a proven mutation (category Arecommendation)." (PMID 28894332, 2017). "The great majority has received a negative test result, yet some still harbor an undiscovered pathogenic BRCA1 or BRCA2 mutation (due to limited sequencing) or a pathogenic mutation in another cancer susceptibility gene." (PMID 28281021, 2017). "Women with BRCA1 or BRCA2 gene mutations should undergo annualbreast cancer screening with mammography from age 30onward, as should women who have first-degree relativeswith a proven mutation (category Brecommendation)." (PMID 28894332, 2017). "BRCA2 suppresses genome instability, a hallmark of cancer, by playing a central role in two processes: homologous recombination (HR) for the repair of DNA lesions and protection of nascent strands at stalled replication forks from degradation." (PMID 28904335, 2017). "To identify potential novel drugs for cancers with BRCA2 mutations, we tested a total of 17 commercially available inhibitors by clonogenic assays in isogenic BRCA2 knockout and wild type (WT) HCT116 cell line pairs published by us21." (PMID 28211448, 2017). "Targeting human RAD52 represents a selective therapeutic approach for BRCA2-deficient cancers due to the synthetic lethality of RAD52 and BRCA2." (PMID 29215575, 2017). "A study has confirmed a role of the FA pathway in supporting the Alt-EJ method of repair in cancers with BRCA1 or BRCA2 deficiencies." (PMID 28239445, 2017). "In this report, we have tried to gain molecular insight into a single nucleotide polymorphism (SNP) in the NEIL2 gene previously identified as “cancer risk modifier” for BRCA2 mutation carriers." (PMID 29383107, 2017). "The BRCA2 protein can regulate homologous recombination by interacting with the RAD51 recombinase, and many studies have suggested that the rs144848 polymorphism in the BRCA2 gene is a susceptibility locus for cancers." (PMID 28418854, 2017). "The BRCA2 gene plays an important role in cancer carcinogenesis, and polymorphisms in this gene have been associated with cancer risk." (PMID 28418854, 2017). "Taken together, our data show that forced bypass of mitosis results in decreased PARP inhibition-induced cytotoxicity, and indicate that progression through mitosis promotes cell death in BRCA2-deficient cancer cells treated with PARP inhibitor." (PMID 28714471, 2017). "Mutations in BRCA1 and BRCA2 render a cancer cell hypersensitive to PARP inhibitors but they can acquire resistance and relapse." (PMID 28714471, 2017). "Patient #2 possessed a germline heterozygous BRCA2 E49* mutation that underwent loss of heterozygosity in the patient’s cancer, a possibly oncogenic FLT4 E766D somatic mutation, and moderate ERBB2 amplification (5 copies) at all timepoints." (PMID 29093439, 2017). "Germline mutations in the BRCA genes (BRCA1, BRCA2) predispose individuals to develop several kinds of cancer, including that of the breast." (PMID 29138528, 2017).
cancer (continued). "In particular, BRCA1 and BRCA2 loss of function have been shown to lead to dysfunctional HR in cancer cells whereas the association between PTEN loss of function and dysfunctional HR is more controversial." (PMID 28002809, 2017). "Stronger tumour growth inhibition to BRCA2 deficient than BRCA2 WT cancers was also observed in xenograft model with tumours formed by DLD1 isogenic cell line pairs." (PMID 28211448, 2017). "Genome-wide studies of patients carrying pathogenic variants (mutations) in BRCA1 or BRCA2 have reported strong associations between single-nucleotide polymorphisms (SNPs) and cancer risk." (PMID 28145423, 2017). "BRCA1 and BRCA2 genes represent paradigmatic examples of tumor suppressors, linking genome instability, and cancer susceptibility." (PMID 29038466, 2017). "The main objective of this study was to determine the mutational spectrum in BRCA1 and BRCA2 genes in Colombia, and compare two diagnostic strategies to detect patients at high risk of developing cancer and establish prevention programs." (PMID 29021639, 2017). "Germline mutations affecting a single copy of the HR factors BRCA1 and BRCA2 predispose individuals to cancers of the breast, ovary, prostate, and pancreas." (PMID 28835508, 2017). "The BRCA2 protein is a fundamental element of HR and somatic mutations in BRCA2 are known cancer drivers." (PMID 28591715, 2017). "BRCA2 encodes a protein with a critical role in homologous recombination and the DNA damage response that is essential for normal development and cancer prevention." (PMID 28617445, 2017). "The BRCA2 rs144848 polymorphism has been associated with several cancers, but results have been inconsistent." (PMID 28418854, 2017). "At the same time, conventional chemotherapy does not show promising outcomes in CRPC patients with a germline breast cancer 2 (BRCA2) mutation." (PMID 28410213, 2017). "BRCA1/BRCA2-associated cancer risk management includes increased cancer surveillance and risk reduction strategies." (PMID 28780755, 2017). "The various related and distinct functions of BRCA1 and BRCA2 have made it difficult to pinpoint the function of these gene products responsible for the closely related cancer phenotypes caused by their gene defects." (PMID 27452521, 2017). "PARP inhibitors allow selective killing of cancer cells because the trapping/cytotoxic effect makes use of deficiencies in DNA repair systems that are unique to individual types of cancer (e.g. BRCA1/BRCA2-deficient tumors), as compared with normal tissue." (PMID 28978150, 2017). "Five of 114 (4.4%) of ER+ HER2+ cancers had mutations (4 BRCA2) and 4/45 (9%) of ER− HER2+ (3 BRCA1)." (PMID 27796713, 2017). "The age distributions are consistent with existing data that BRCA1 and BRCA2 mutation carriers tend to suffer cancer at earlier age." (PMID 27148484, 2016). "BRCA1/BRCA2-deficient cancers are now recognized as the target for a class of drugs known as PARP (poly (ADP-ribose) polymerase) inhibitors." (PMID 27532258, 2016). "Other studies provided an important role for mammographic textures such as fractal dimensions, GLCM matrix parameters, and power Fourier spectrum in distinguishing between BRCA1/BRCA2 gene mutations and cancer risks." (PMID 27923387, 2016). "6-OH-dopa inhibited RAD52 foci formation in response to DNA damage in murine hematopoietic cells deficient in BRCA1 and selectively killed BRCA1 and BRCA2-deficient human cancer cells." (PMID 27649245, 2016). "BRCA2 has numerous roles in maintaining the genome to prevent accumulation of mutations that can lead to cancer formation." (PMID 27490902, 2016).
cancer (continued). "Women carrying a pathogenic germline mutation in the BRCA1 and BRCA2 genes have an increased lifetime risk of developing breast, ovarian, and several other cancers." (PMID 27553291, 2016). "We describe here a case of ACC associated with a germline BRCA2 mutation in a family whose cancer history was compatible with a Li-Fraumeni-like (LFL) syndrome." (PMID 27603373, 2016). "In cell lines, secondary somatic mutations in BRCA1- or BRCA2-mutant cancer cells can restore protein expression, reconstitute HR, and confer resistance to PARPi and platinum." (PMID 27634150, 2016). "BRCA2 mutations strongly increase the in vitro- and in vivo-sensitivity of cancer cells towards TRAIL-R-mediated apoptosis." (PMID 26843614, 2016). "The effects of TRAIL-R-targeting compounds and ICL-agents on cell viability, apoptosis and cell cycle distribution were compared in BRCA2-proficient versus-deficient cancer cells in vitro." (PMID 26843614, 2016). "Of note, BRCA2-deficient cancer cells displayed a significantly stronger hypersensitivity towards TRAIL-R stimulation using LBY135 than towards the classical ICL-agent MMC in our studies." (PMID 26843614, 2016). "Mutations in the BRCA1/BRCA2 genes have also been associated with inherited predisposition to other cancers in HBOC families, like those of the prostate, pancreas, male breast, peritoneum, and fallopian tube." (PMID 27532258, 2016). "Given the well-established BC risks for BRCA1 and BRCA2 mutations, a multiplicative model would imply very high cancer risk at young ages." (PMID 27836010, 2016). "Presymptomatic salpingo-oophorectomy and mastectomy for female BRCA1 and BRCA2 mutation carriers after child-bearing age can significantly reduce morbidity and mortality of these two cancers." (PMID 26867194, 2016). "In conclusion, our data demonstrate that BRCA2-deficiency - modeled by two independent experimental techniques - confers increased sensitivity towards TRAIL-R-stimulation in cancer cell lines in vitro and in vivo." (PMID 26843614, 2016). "2R/1R (OR = 1.94, 95%CI = 1.14–3.32, P = 0.0242) was associated with increased risk in cancer-affected BRCA2+ group." (PMID 27148484, 2016). "Further work is needed to demonstrate the efficacy of RAD52 inhibitors in killing BRCA1- and BRCA2-deficient cancer cells in vivo." (PMID 27649245, 2016). "AZD2281 Olaparib (kuDOS/LynparzaTM, AstraZeneca), used for oral administration, is the first inhibitor identified as single antitumoral agent in cancer associated with the BRCA1 or BRCA2 mutations." (PMID 27884198, 2016). "In vivo, treatment with LBY135 significantly reduced the tumor growth of BRCA2-deficient cancer cells in a xenograft model." (PMID 26843614, 2016). "Our findings suggest that while complete loss of BRCA2 is clearly associated with increased risk of breast, ovarian and other cancers, hypomorphic alleles that disrupt key BRCA2 functions, are likely to be equally pathogenic." (PMID 27490902, 2016). "The in vitro results were consecutively validated in vivo using LBY in a murine xenograft model of BRCA2-deficient cancer cells." (PMID 26843614, 2016). "Functional characterization of cancer-causing mutations in PALB2 suggested that the C-terminal region containing four WD40 motifs binds to BRCA2." (PMID 27490902, 2016). "For example, mutations in BRCA1 and BRCA2 have long been known to confer cancer susceptibility and women with a germ-line heterozygous mutation have an overall increased lifetime risk of developing breast and ovarian cancers." (PMID 27788678, 2016). "In early studies, including a small number of tumor samples obtained from large BC and OC families, it was suggested that greater than 85 % of BRCA1- or BRCA2-associated cancers exhibited LOH, and all showed loss of the normal allele." (PMID 27836010, 2016).
cancer (continued). "For instance, Olaparib resistance was conferred in BRCA2-deficient cancers harboring frame-shift mutations through subsequent mutations that restored the BRCA2 reading frame to effectively/partially rescue the HRR defect." (PMID 27902462, 2016). "A particular class of drugs, poly(ADP-ribose) polymerase-inhibitors (PARPi), has been shown to be effective for targeted treatment of cancers harbouring BRCA1 or BRCA2 mutations." (PMID 26745875, 2016). "Perhaps the most interesting aspect of our study was the recurrent finding of germline BRCA2 mutations in carcinomas of the ampullary region." (PMID 27532258, 2016). "The increasingly recognized involvement of germline mutations in BRCA1 and BRCA2 in diverse cancers, as well as the active design of targeted therapies, further adds to the need to recruit minority subjects." (PMID 26543556, 2015). "In Canada, all genetic testing for BRCA1 and BRCA2 must be ordered by a cancer genetics professional associated with a cancer medical genetics clinic, where clinics are managed by provincial health care jurisdictions." (PMID 25884701, 2015). "BRCA1 mutation-positive carriers were identified among all subtypes except for undifferentiated adenocarcinomas, whereas BRCA2 mutation-positive cases were identified among the serous and undifferentiated adenocarcinoma subtype cancers." (PMID 25884701, 2015). "BRCA1 and BRCA2 (breast cancer susceptibility genes 1 and 2) genes encode for tumour suppressor proteins important in DNA repair pathways." (PMID 26056364, 2015). "Risk models that incorporate both BRCA1 and BRCA2 mutations and other sources of variation are required to provide accurate estimates of mutation carrier probabilities and cancer risk for use in genetic counselling." (PMID 26025000, 2015). "Examples of BRCA1 mutation carriers were found among women with serous, endometrioid and mixed cell subtype cancers in contrast to BRCA2 mutation carriers, who were found to have had either serous or undifferentiated adenocarcinomas." (PMID 25884701, 2015). "A review of the BRCA1 and BRCA2 mutation spectrum found in French Canadian cancer families where comprehensive analysis was performed supports this strategy." (PMID 25884701, 2015). "One of the major advancements in cancer research was the discovery of the breast cancer susceptibility gene 1 (BRCA1) and the breast cancer susceptibility gene 2 (BRCA2)." (PMID 26236408, 2015). "We detected 53 BRCA1 rare truncation variants across 7 cancer types and 50 BRCA2 rare truncation variants across 6 cancer types." (PMID 26689913, 2015). "One of the limitations of PARP therapy is that there are limited numbers of cancer patients with BRCA1 or BRCA2 mutation." (PMID 25769025, 2015). "All previously known BRCA1 and BRCA2 variants in the specimens were successfully detected by both platforms and in all 3 validation runs (i.e., 100% accuracy for cancer-associated mutations)." (PMID 26295337, 2015). "Considering any somatic mutation, we found that BRCA2 somatic mutations (chr 13) occurred before CN events with F = 0.98 [0.85–1.16] (Pwilcox = 0.125), based on four carcinomas." (PMID 25916844, 2015). "Three tumours with the highest ploidy had little genome-wide LOH, yet one of these had a homozygous somatic frame-shift BRCA2 mutation, suggesting that some carcinomas begin as tetraploid then descend into diploidy accompanied by genome-wide LOH." (PMID 25916844, 2015). "Patient P had a germline frameshift mutation in BRCA2 that became homozygous in the carcinoma, suggestive of a potentially deleterious mutation." (PMID 25916844, 2015).